AFP (alpha fetoprotein)
Diseases named in the same sentence as AFP in open-access papers (continued):
Sharing a sentence is not in itself a finding about the gene and the disease.
hepatocellular carcinoma (continued). "Factors influencing the survival of hepatocellular carcinoma (HCC) patients include portal vein thrombosis (PVT), tumor numbers (multifocality), blood alpha-fetoprotein (AFP) levels, and the degree of liver damage (levels of blood bilirubin and albumin)." (PMID 33546234, 2021). "The serum AFP in APA patients is increased (>20ng/ml) and markers representing embryonic stem cells and hepatocellular carcinoma in tumor tissues, such as AFP protein, glypican-3, Sal-like protein-4, and/or hepatocyte antigen-1, are positive." (PMID 33996549, 2021). "The endocytosed AFP can interact with PTEN and activate the PI3K/AKT/mTOR pathway, which promotes the malignant behavior of hepatocellular carcinoma (HCC) cells by upregulating the protein expression of mTOR." (PMID 33718192, 2021). "Despite moderate sensitivity, alpha fetoprotein (AFP) is widely used in screening and prognostication for hepatocellular carcinoma (HCC)." (PMID 34181327, 2021). "However, with the rapid development of medical imaging, the proportion of diagnosed small hepatocellular carcinoma is increasing, and the sensitivity of AFP is gradually decreasing, with AFP at normal or low levels in 30–40% of HCC patients." (PMID 34846705, 2021). "Among the prognosis prediction models developed to date, the hepatoma arterial embolization prognostic (HAP) score consists of a point system according to tumor size, alpha-fetoprotein (AFP), bilirubin, and albumin." (PMID 35008231, 2021). "We aimed to describe clinical characteristics of ESLD from cirrhosis or hepatocellular carcinoma (HCC) and the performance of aspartate aminotransferase (AST)—platelet ratio index (APRI) and alpha fetoprotein (AFP) in Ghana." (PMID 33357229, 2020). "For alpha-fetoprotein (AFP), a biomarker of hepatocellular carcinoma (HCC), two DNA aptamers were described with very different affinity." (PMID 32365872, 2020). "The Japan criteria (JC, maximum tumor size within 5 cm, within five tumor nodules, AFP within 500 ng/mL or within Milan criteria) have been applied to cadaveric liver transplantation (LT) for hepatocellular carcinoma (HCC) and will be used for living donor LT (LDLT) in Japan." (PMID 32724885, 2020). "Alpha fetoprotein (AFP) has been used as a serologic indicator of hepatocellular carcinoma (HCC)." (PMID 31979338, 2020). "Studies have found that cytoplasmic AFP can combine with PTEN to promote the onward transmission signalling of the PI3K/AKT signalling, which leads to aberrant growth of hepatocellular carcinoma cells." (PMID 33090723, 2020). "Similarly, DCexos derived from α-fetoprotein (AFP)-expressing DCs have been shown to induce allogeneic anti-tumor immunity in a hepatocellular carcinoma (HCC) mouse model." (PMID 33255895, 2020). "According to imaging manifestations, pathological immunohistochemical treatment, alpha fetoprotein (AFP) and clinical features, hepatic adrenal tumors should be considered in the diagnosis of hepatic carcinoma to prevent misdiagnosis." (PMID 32522174, 2020). "AFP, Hepatocyte and GPC3 proteins are specific immunohistochemical factors for the diagnosis of hepatocellular carcinoma, while CK19 and CK7 are specific immunohistochemical factors for the diagnosis of cholangiocellular carcinoma." (PMID 32967689, 2020). "Tumor markers such as AFP, CA 19-9, and CEA are within normal range in almost 100% of cases, helping to differentiate PHL from hepatocellular carcinoma or metastatic disease." (PMID 32977834, 2020). "Dexosomes from α-fetoprotein (AFP)-expressing DCs have been shown to exhibit efficient anti-tumor activity in transplantable, orthotopic and carcinogen-induced hepatocellular carcinoma (HCC) mouse models." (PMID 32765528, 2020). "In summary, AFP interferes with the cascade conduction of the RA‐RAR signalling pathway by regulating the transcription factor RAR, thus reducing the sensitivity of hepatoma cells to the chemotherapy drug ATRA." (PMID 33090723, 2020).
hepatocellular carcinoma (continued). "In an oncopig model of hepatocellular carcinoma (HCC), alpha feto protein (AFP) was reliably used for detection of swine HCC as well as treatment monitoring." (PMID 31293961, 2019). "Little is known about the association between cancer antigen 125 (MUC16/CA125) concentrations and tumor diameter of patients with hepatocellular carcinoma (HCC) and low AFP levels." (PMID 31662990, 2019). "We examined the mRNA expression levels of several hepatocyte/hepatoma markers, such as albumin, ApoA1, CYP3A4, HNF4α, OATP1B3, and AFP in both cell lines and in lung carcinoma-derived A549 cells by qRT-PCR." (PMID 31138826, 2019). "The most common primary hepatic malignancy is hepatocellular carcinoma (HCC), and it is predicted by a gold standard diagnostic biomarker AFP, although the lack of sensitivity has challenged its use." (PMID 31363116, 2019). "In this study, we evaluated AFP, CA19-9 and CEA levels as well as positive rates, sensitivity and specificity of the serum markers in diagnosing hepatocellular carcinoma to establish a potential prognostic correlation between their serum levels." (PMID 31205886, 2019). "Portal Venous Thrombosis (PVT) is a common complication of Hepatocellular Carcinoma (HCC), assessed as adverse prognostic factor and parameter of tumor aggressiveness together with tumor size, multifocality and Alpha-fetoprotein (AFP) levels." (PMID 31141552, 2019). "Alpha-fetoprotein (AFP) is the most commonly used biomarker for early screening and diagnosis of hepatocellular carcinoma (HCC)." (PMID 31921529, 2019). "Alpha-fetoprotein (AFP) is still the most commonly used and the single most recommended marker in the diagnosis of hepatocellular carcinoma (HCC)." (PMID 29963457, 2018). "Serum alpha‐fetoprotein (AFP) is the most commonly used tumor biomarker for screening and diagnosis of primary hepatocellular carcinoma (HCC)." (PMID 29696820, 2018). "We previously developed a logistic regression algorithm that uses AFP, age, gender, ALK and ALT levels to improve the detection of hepatocellular carcinoma (HCC)." (PMID 30169533, 2018). "Alpha fetoprotein (AFP) is a biomarker for germ cell tumor, hepatocellular carcinoma and certain gastric carcinomas." (PMID 29160798, 2017). "The purpose of this study was to conduct a comprehensive study of the clinical correlation between the alpha-fetoprotein (AFP) level at diagnosis and pathological grades, progression, and survival of patients with hepatocellular carcinoma (HCC)." (PMID 28993684, 2017). "Among the different GC subtypes, GHAC has comparable histology and functionality to stem cell differentiation, it has pathologically similar tissue morphology to hepatocellular carcinoma (HCC), and it frequently expresses alpha-fetoprotein (AFP) on immunohistochemistry." (PMID 28545511, 2017). "As an indicator of hepatocellular carcinoma (HCC), high levels of α-fetal protein (AFP) are related to malignant differentiation and poor prognosis of cancer cells." (PMID 29095434, 2017). "Among these proteins, there are some well-known features like alpha-fetoprotein (FETA) or glypican-3 (GPC3) and potential hepatocellular carcinoma (HCC) markers." (PMID 29168748, 2017). "Although alpha-fetoprotein (AFP) is the most widely used biomarker in hepatocellular carcinoma (HCC) surveillance, disease activity may also increase AFP levels in chronic hepatitis B (CHB)." (PMID 27997559, 2016). "Cytoplasmic AFP has the ability to disrupt the onward transmission signaling of the RA- RAR and PI3K/AKT signaling, which leads to aberrant growth of hepatocellular carcinoma cells." (PMID 27835879, 2016).
hepatocellular carcinoma (continued). "Due to good drug-loading, high encapsulation ratio, and highly selective affinity for AFP-positive tumors, the 131I-antiAFPMcAb-GCV-BSA-NPs are promising for further effective radiation-gene therapy of hepatoma." (PMID 26981334, 2016). "In this study, we explored the possible mechanism of miRNAs on post-transcriptional regulation of AFP gene, as well as the effects of HBV infection and icaritin in hepatoma cells." (PMID 27835879, 2016). "CHB, chronic hepatitis B; LC, liver cirrhosis; HCC, hepatocellular carcinoma; SD, standard deviation; ALT, alanine aminotransferase; AST, aspartate aminotransferase; AFP, alpha-fetoprotein." (PMID 26599409, 2015). "Alpha-fetoprotein (AFP)-producing adenocarcinoma, histologically mimicking hepatocellular carcinoma (HCC), is a distinct entity known as hepatoid adenocarcinoma (HAC)." (PMID 26094198, 2015). "Recent data displayed that GOLPH2 is a superb hepatocellular carcinoma (HCC) marker candidate, and even its specificity is better than liver cancer marker AFP." (PMID 25980438, 2015). "We found that the expression of Sgo1 mRNA was relatively low in normal tissues, but was upregulated in 82% of hepatocellular carcinoma (HCC), and correlated with elevated alpha-fetoprotein and early disease onset of HCC." (PMID 25638162, 2015). "Ultimately, the experimental results and the molecular modeling data from the interactions of AFP and HSA with PTEN will help us to identify targets for designing drugs and vaccines against human hepatocellular carcinoma." (PMID 26078940, 2015). "However, AFP in adult serum is undetectable except in patients who suffer from hepatocellular carcinoma (HCC)." (PMID 25105025, 2014). "We evaluated treatment modalities and survival in patients with hepatocellular carcinoma (HCC), by pre-treatment and 3-month post-treatment serum alpha-fetoprotein (AFP) levels and pre-treatment tumor diameters." (PMID 24993566, 2014). "Decreased body weight and increased serum AFP concentration, ALT, AST, and ALP activity confirmed induction of hepatocellular carcinoma in DEN+2-AAF treated rat group." (PMID 25136637, 2014). "For example, alpha-fetoprotein (AFP) is one of the clinically useful biomarkers for the diagnosis and follow-up of hepatocellular carcinoma (HCC).AFP was elevated above 20 ng/mL in one study in more than 70% of patients with HCC." (PMID 24404153, 2014). "According to the “diagnosis and treatment norms of primary hepatic carcinoma” that was issued by ministry of health of the PRC in 2011, AFP level of more than 400 ng/mL is a cut-off value to diagnose primary hepatic carcinoma." (PMID 25275448, 2014). "Zinc fingers and homeoboxes 2 can regulate alpha-fetoprotein expression via the interaction with nuclear factor-YA in human hepatocellular carcinoma and may be used as an adjuvant diagnostic marker for alpha-fetoprotein-negative hepatocellular carcinoma." (PMID 23533382, 2013). "In effort to found more sensitive and specific tumor marker for hepatocellular carcinoma, the levels of A1AT and levels of alpha-fetoprotein (AFP) were combined." (PMID 23162602, 2012). "Alpha-fetoprotein (AFP), des-γ-carboxy prothrombin (DCP), and lens culinaris agglutinin-reactive fraction of AFP (AFP-L3) have been developed with the intent to detect hepatocellular carcinoma (HCC) and for the surveillance of at-risk patients." (PMID 22792474, 2012). "These combined levels were found to be more sensitive and more specific tumor marker for hepatocellular carcinoma, than separate A1AT and AFP levels." (PMID 23162602, 2012). "Alpha-fetoprotein (AFP) is an oncofetal protein produced by hepatocellular carcinoma (HCC)." (PMID 22559879, 2012). "In this study, DCs from hepatocellular carcinoma (HCC) patients were co-transfected with the IL-2 gene and/or the AFP gene." (PMID 23170121, 2012).
hepatocellular carcinoma (continued). "Previously, we tested a peptide-pulsed DC vaccine to promote Alpha-fetoprotein (AFP-) specific anti-tumor immunity in patients with hepatocellular carcinoma (HCC), and reported on the CD8+ T cell responses induced by this vaccine and the clinical trial results." (PMID 21969837, 2011). "Currently available tumor markers for hepatocellular carcinoma (HCC) are α-fetoprotein (AFP), lens culinaris agglutinin-reactive AFP (AFP-L3), and des-γ-carboxy prothrombin (DCP)." (PMID 21892326, 2008). "The search for tumour antigens began in the 1960's with two groups identifying first alpha-fetoprotein (AFP), a serum marker for hepatoma and germ-cell tumours, and then carcinoembryonic antigen (CEA), a serum marker for colon and other epithelial cancers." (PMID 15715909, 2005). "The α-fetoprotein promoter (AFP) is a representative one to activate an exogenous gene specifically in hepatocellular carcinoma (HCC) and has been applied to targeted gene therapy for HCC." (PMID 12966430, 2003). "The effects of various chemotherapeutic agents on alpha-fetoprotein (AFP) secretion and growth of human hepatocellular carcinoma and hepatoblastoma cell lines were investigated in vitro." (PMID 2469455, 1989). "Hepatocellular carcinoma (HCC) remains a leading cause of mortality in patients with advanced chronic liver disease (ACLD), particularly in those with decompensated cirrhosis, where traditional biomarkers such as alpha-fetoprotein (AFP) often fail to reliably detect malignancy." (PMID 42073372, 2026). "Third, benchmarking against hepatocellular carcinoma (HCC) reinforces plausibility: classic AFP‐plus‐size nomograms in HCC achieve AUCs around 0.78, and deep‐learning radiomics may climb beyond 0.85 —values congruent with the upper bound we observe for a purely laboratory‐based tool." (PMID 41331584, 2025). "used Lasso Cox regression to establish a nomogram of alpha-fetoprotein-negative hepatocellular carcinoma patients without surgery." (PMID 40265018, 2025). "The current noninvasive prognostic evaluation methods for hepatocellular carcinoma (HCC), which are largely reliant on radiographic imaging features and serum biomarkers such as alpha-fetoprotein (AFP), have limited effectiveness in discriminating patient outcomes." (PMID 40279344, 2025). "Imaging and alpha-fetoprotein (AFP) testing excluded hepatocellular carcinoma, and no acute complications of cirrhosis were identified." (PMID 41523421, 2025). "Previous predictive models have primarily focused on comparative studies involving AFP-negative hepatocellular carcinoma patients and healthy individuals." (PMID 40161339, 2025). "Hepatocellular carcinoma screening should be performed every six months using serum alpha-fetoprotein levels and liver ultrasound in patients without hepatic nodules or with multiple nodules identified on MRI." (PMID 41393693, 2025). "The accuracy of EV-LINC00853 was more evident in hepatocellular carcinoma, where the traditional serum biomarker alpha-fetoprotein was not expressed." (PMID 38586313, 2024). "While AFP is commonly used in patients with hepatocellular carcinoma, there is a lack of literature reporting its utility in CRC patients." (PMID 38913246, 2024). "Hepatocellular carcinoma (HCC) presents a significant global health challenge due to limited early detection methods, primarily relying on conventional approaches like imaging and alpha-fetoprotein (AFP)." (PMID 38279264, 2024). "Patients with AFP-negative hepatocellular carcinoma (ANHCC) often present with small tumor sizes or are in the early stages of the disease, exhibiting minimal clinical symptoms." (PMID 38832035, 2024). "Similarly, the sixfold induced alpha fetoprotein expression likely contributed to PTEN inhibition and, therefore, stimulated PI3K/Akt/mTOR signaling as shown for human hepatoma cell lines." (PMID 38245882, 2024).
hepatocellular carcinoma (continued). "This study aims to describe the diagnostic performance of alpha-fetoprotein (AFP), alpha-fetoprotein L3 isoform (AFP-L3), protein induced by vitamin K absence II (PIVKA-II), and combined biomarkers for non-B non-C hepatocellular carcinoma (NBNC-HCC)." (PMID 37932802, 2023). "Hepatocellular carcinoma was ruled out, as evidenced by hernormal alpha-fetoprotein (AFP) level and lack of imaging findings." (PMID 36691914, 2023). "In this model, the chronic administration of DEN+2-AAF induces characteristic alterations of hepatocellular carcinoma in Wistar rats without AFP gene expression changes, highlighting different signatures in hepatocellular carcinoma heterogeneity." (PMID 37176094, 2023). "Serum biomarkers are used to help identify patients early, such as alpha-fetoprotein for hepatocellular carcinoma or CA19.9 for pancreatic cancer; however, these are not sensitive or specific enough to be a reliable diagnostic test." (PMID 37190235, 2023). "AFP is positive in about 70% of patients with hepatocellular carcinoma, and negative in about 30% of patients with hepatocellular carcinoma." (PMID 37312022, 2023). "For example, the serum level of fucosylated α-fetoprotein (AFP), but not AFP alone, allows successful discrimination between hepatocellular carcinoma (HCC) and benign live diseases." (PMID 36746966, 2023). "The diagnosis of hepatoblastoma and hepatocellular carcinoma in our patient was not supported by the normal AFP." (PMID 37482619, 2023). "Moreover, the expression of PPP1R1B, TMEM45B, AFP, and ENPEP followed the same pattern in vitro using human hepatoma (HEPG2) and mouse liver 12 (AML12) cell lines incubated with squalene, indicating a direct effect of squalene on these expressions." (PMID 37628732, 2023). "Patients with hepatocellular carcinoma are AFP-negative up to 50%, thus AFP has low sensitivity and specificity for hepatocellular carcinoma screening." (PMID 37848835, 2023). "By incorporating three preoperative MRI features and serum AFP, the OSASH score may help predict postsurgical overall survival in patients with hepatocellular carcinoma and identify potential surgical candidates among those with BCLC stage B and C HCC." (PMID 37191923, 2023). "Univariate and multivariate analysis to identify independent influencing factors affecting the diagnosis of AFP-negative hepatocellular carcinoma." (PMID 36890811, 2023). "They found that transfection of AFP-cDNA into hepatoma HLE cells (originally AFP-negative) led to a significant activation of the Akt signaling pathway." (PMID 37588998, 2023). "Considering both tumor- and liver function-related factors, the hepatoma arterial-embolization prognostic (HAP) score (including tumor size, bilirubin, albumin, and α-fetoprotein (AFP)) has exhibited a promising prediction performance in uHCC patients following TACE." (PMID 36776366, 2022). "First-line surveillance on hepatitis B virus (HBV)-infected populations with B-mode ultrasound is relatively limited to identifying hepatocellular carcinoma (HCC) without elevated α-fetoprotein (AFP)." (PMID 35720017, 2022). "The purpose of this study was to compare the diagnostic value of serum oligosaccharide chain (G-test), alpha-fetoprotein (AFP) and aspartic aminotransferase to alanine aminotransferase ratios (AAR), both alone and in combination, for predicting hepatocellular carcinoma (HCC) onset." (PMID 36241994, 2022). "In the clinical application of hepatocellular carcinoma (HCC), traditional diagnostic methods such as serum AFP have limited specificity and sensitivity, and current data show that there is no single biomarker for the diagnosis of HCC, especially in the inchoate stage of development." (PMID 36425563, 2022).